DNMT3A (DNA methyltransferase 3 alpha)
Diseases named in the same sentence as DNMT3A in open-access papers (continued):
Sharing a sentence is not in itself a finding about the gene and the disease.
Obesity (continued). "Adipose-specific expression of Dnmt3a in mice did not significantly affect the DNA methylation, while gene expression of inflammatory cytokines was higher, suggesting that Dnmt3a might regulate obesity-related inflammation in mice." (PMID 34968255, 2021). "Now, in eLife, Sona Kang, Evan Rosen and colleagues in the USA, Denmark and Sweden – including Dongjoo You of the University of California Berkeley as first author – report how a key epigenetic regulator called Dnmt3a contributes to obesity-related insulin resistance." (PMID 29239299, 2017). "Furthermore DNMT3a was found to bind to the SIRT1 promoter, suggesting that the RRTFB may regulate SIRT1 methylation by inhibiting DNMT3a activity, thereby mitigating obesity‐associated inflammation and oxidative stress." (PMID 40909259, 2025). "First, the mechanism underlying the upregulation of Dnmt3a in obesity is not clear." (PMID 29239299, 2017). "Therefore, targeting Dnmt3a or Fgf21 could provide new treatment opportunities for obesity-related complications such as insulin resistance." (PMID 29239299, 2017). "Here, we demonstrate in a mouse model that CH driven by Dnmt3a RH and especially LOF promotes obesity, diabetes, and chronic liver disease, effects that are further exacerbated by high-fat diet (HFD)." (PMID 41027007, 2025). "In addition, the expression of DNMTs (DNMT1, DNMT3a and DNMT3b) was quantified because they encoded the main enzymes involved in the methylation of DNA and previously we have detected a regulation of these genes after following a VLCKD in blood leukocytes of patients with obesity." (PMID 40140215, 2025). "Mouse models of obesity and CHIP driven by heterozygosity of Tet2, Dnmt3a, Asxl1, and Jak2 resulted in exacerbated expansion of mutant HSC/Ps due in part to excessive inflammation." (PMID 37071471, 2023). "Together these data from heterozygous Dnmt3a KO mice mirror the findings in TBRS patients of increased size and marked obesity that develops after adolescence." (PMID 35635747, 2022). "Recently, obesity-induced hypermethylation at adiponectin and Fgf21 genes mediated by DNMT1 and DNMT3A, respectively, was shown to play an important role in the pathogenesis of insulin resistance in adipose tissue." (PMID 33235221, 2020). "In a diet-induced obesity (DIO) mouse model, Dnmt1 and Dnmt3a mRNA expression was elevated in adipose tissue, especially in epididymal and mesenteric WAT." (PMID 29091029, 2017). "Literature data report that obesity can increase DNMT expression and activity and that increased expression of Dnmt3a in the adipose tissue may contribute to obesity-related inflammation." (PMID 35624758, 2022). "Furthermore, mice in which Dnmt3a was specifically ablated in adipocyte progenitors showed enlarged fat depots and increased progenitor numbers, partly recapitulating the TBRS obesity phenotypes." (PMID 35635747, 2022). "Despite some effort, we have not yet identified the mechanism by which Dnmt3a expression is increased in obesity." (PMID 29091029, 2017).
colorectal cancer (35 papers, 2010 to 2025). A primary or metastatic malignant neoplasm that affects the colon or rectum. "In colorectal cancer, DNA methyltransferase DNMT3A was found to be associated with infiltration of six major immune cells." (PMID 37400791, 2023). "In contrast, increased DNMT3B expression has been reported in colorectal cancer, while the deletion of Dnmt3a inhibits colorectal cancer development." (PMID 39819598, 2025). "For example, in colorectal cancer, Circ_0084615 upregulated DNMT3A expression through the sponge miR-599 to promote the proliferation, migration, and invasion of colorectal cancer cells." (PMID 37781524, 2023). "The decreased expression of miR-143 in colorectal cancer cells results in the increased activity of methyltransferase 3A DNA (DNMT3A) and the increased proliferation of cancer cells." (PMID 35627259, 2022). "A work performed on colorectal cancer cells reported that different concentrations of Doxorubicin are able to induce apoptosis or senescence and that DNMT3A plays a key role in this switch through the regulation of p21." (PMID 34831178, 2021). "Recent studies have revealed that the lncRNA PART-1 was up-regulated in colorectal cancer, functioned as a competitive endogenous RNA to regulate the targeted gene DNMT3A by sponging miR-143, participated in colorectal cancer cell proliferation and metastasis." (PMID 29420609, 2018). "Ectopic expression of miR-143 in breast cancer cells or restoring expression of miR-143 in colorectal cancer cell lines repressed the Dnmt3a expression at both mRNA and protein levels." (PMID 29170626, 2017). "To observe the consequences of PADI4-mediated DNMT3A upregulation specifically, we used the colorectal cancer cell line HCT-116, where both the DNMT1 and DNMT3B DNMTs have been genetically disrupted (DKO cells) and where DNMT activity is minimal." (PMID 24957603, 2014). "To confirm that DNMT3A could regulate the expression of p16 in colorectal cancer, we knockdown the DNMT3A in SW480 and HCT116 cells." (PMID 39284825, 2024). "It was demonstrated that recruiting DNA methyltransferase DNMT3a to the promoter of MIR137 in colorectal cancer cells could lead to suppression of MIR137 expression." (PMID 37223641, 2022). "Thus, decreased miR-34a expression contributes to a miR-449a-mediated negative feedback loop to maintain low levels of miR-449a/34a and high levels of SATB2, Sirt1, HDAC1 and DNMT3a in colorectal cancer cells." (PMID 29254139, 2017). "Interestingly, miR-143 in the breast and colorectal cancer tissues affected the Dnmt3a expression at both mRNA and protein levels." (PMID 29170626, 2017). "DNMT3A encodes a DNA methyltransferase that is thought to function in de novo methylation, rather than maintenance methylation, which impacts the expression of p21 and plays a role in determining doxorubicin-induced senescence and apoptosis in HCT116 colorectal cancer cells." (PMID 32127798, 2020). "However, and surprisingly given our findings, recent work in mouse ESCs, derived neuronal progenitors, and the human colorectal carcinoma HCT116 cell line have showed that it is principally DNMT3B (and to a lesser extent DNMT3A) that is associated with gene-body methylation." (PMID 26408185, 2015). "However, it has been recently shown that DNMT3A could play a role in anthracyclines-induced apoptosis of colorectal cancer cells." (PMID 22081665, 2011). "The ELFN1-AS1 lncRNA interacts with repressive PRC2 and DNMT3A and targets the Meis Homeobox 1 (MEIS1) promoter region in colorectal cancer cells." (PMID 40141189, 2025). "In colorectal cancer, HIF1A-AS2 competitively sponges miR-129-5p to upregulate DNA methyltransferase 3 alpha (DNMT3A)." (PMID 34557530, 2021). "Similar to DNMT1, DNMT3a also have strong staining in the epithelial cells of PJS polyps and colorectal cancer in PJS patients compared to the normal samples." (PMID 32799895, 2020).
colorectal cancer (continued). "Likewise, in other models (i.e., colorectal cancer cells), DAC increased DNMT3A and TETs gene expression." (PMID 38966230, 2024). "To determine whether UHRF2 and UHRF1 also negatively regulate DNMT3A in human cancer cell lines, we knocked down UHRF2 or UHRF1 in cervical cancer HeLa and colorectal cancer HCT116 cells by lentiviral-mediated shRNA infection." (PMID 27462454, 2016). "In addition, colorectal carcinoma (CRC) cells which were subjected to hypoxia and hypoglycemia had reduced DNMT1, DNMT3a, and DNMT3b mRNAs, resulting in a decrease in the 5mC level at the proximal promoter region of p16INK4a." (PMID 26861406, 2016). "Therefore, HSF1 regulated DNMT3a/MIR137HG/MIR137 / GLS axis to raise glutaminolysis and mTOR activation and promote the process of colorectal cancer, and it is a potential therapeutic target for colorectal cancer." (PMID 37127605, 2023). "Part of the de novo DNMT activity we measure at H3K36me3 marked CGIs in colorectal cancer cells could therefore be mediated by DNMT3A rather than DNMT3B but is primarily dependent on DNMT3B for recruitment." (PMID 33514701, 2021).
colon carcinoma (32 papers, 2008 to 2025). "In a mouse model that combines colitis-associated colon cancer (CAC) with experimental CH driven by Dnmt3a+/Δ, we found higher tumor penetrance and increased tumor burden compared with controls." (PMID 37615936, 2023). "Since both DNMT1 and DNMT3a are unable to compensate for DNMT3b loss, it is plausible that colon carcinoma cells contain an unidentified component of the DNA methylation pathway which is absent in PC3 cells." (PMID 18798999, 2008). "We hypothesized that bone marrow–derived cells with heterozygous loss-of-function mutations of DNMT3A, the most common genetic alteration in CH, contribute to the pathogenesis of colon cancer." (PMID 37615936, 2023). "Thus, in myeloid leukemia samples, the frequency of DNMT1 and DNMT3A mutations was high, whereas, in glioblastoma, renal cell carcinoma, and colon carcinoma, the total mutation rate was less than 9%." (PMID 34572812, 2021). "DNMT3A overexpression also correlated with a higher risk for relapse in colon cancer." (PMID 33323965, 2021). "Treatment with the angiogenesis inhibitor axitinib eliminated the colon tumor-promoting effect of experimental CH driven by Dnmt3a haploinsufficiency and rebalanced hematopoiesis." (PMID 37615936, 2023). "In this proof-of-concept study, we report that heterozygous inactivation of Dnmt3a restricted to the hematopoietic compartment exacerbates the development of colon cancer phenotype in an inflammation-induced mouse model." (PMID 37615936, 2023). "The Transwell assay data showed that the overexpression of DNMT3A partially reversed the decrease in the migration and invasion abilities of colon cancer cells that had been induced by TDG overexpression." (PMID 35414793, 2022). "For example, MTA1 and DNMT3a mRNA levels are significantly upregulated (p = 0.004) and downregulated (p = 3.00E-4) respectively, in gastric, renal, ovarian, skin and colon cancers when compared to the normal tissues." (PMID 28393842, 2017). "The noted inverse relationship between the levels of MTA1 and DNMT3a mRNAs was not limited to human breast or colon cancer but true for cancer, at-large, in general, when compared with the corresponding normal tissues using Oncomine dataset." (PMID 28393842, 2017). "More recently, it has been reported that Dnmt1 localizes to mitochondria in cultured mouse embryonic fibroblasts and human colon carcinoma cells and that Dnmt3a localizes to mouse brain and spinal cord mitochondria." (PMID 24399935, 2013). "The results are similar to those of reports that arsenic trioxide inhibits DNMT1 protein in human liver and colon cancer cells, we found that arsenic trioxide also inhibits DNMT3a protein in ER-negative breast cancer cells." (PMID 22558281, 2012). "An inverse correlation of expression between miR-143 and DNMT3A mRNA was observed in all colon cancer cell lines (r=−0.78, P=0.048; Spearman's correlation)." (PMID 19638978, 2009). "Therefore, we propose that TDG can inhibit the migration and invasion abilities of colon cancer cells by reducing their level of DNMT3A, decreasing the TIMP2 promoter methylation, and increasing the expression of TIMP2." (PMID 35414793, 2022). "DNA methylation changes mediated by DNMT3a are characteristic of colon cancers." (PMID 26133168, 2015). "Thus, DNMT3A dysregulation in cigarette smokers may be involved in the initiation of lung and colon cancer pathogenesis." (PMID 40003580, 2025). "Dnmt1, but not Dnmt3a, was found associated with mitochondria from cultured mouse embryonic fibroblasts and human colon carcinoma cells, but mitochondrial surface-associated Dnmt1 was not ruled out by protease digestion of outer membrane-bound proteins as done here." (PMID 24399935, 2013).
colon carcinoma (continued). "DNMT3A overexpression partially rescued the TDG-induced decrease in the migration and invasion abilities of colon cancer cells, and rescued the TDG-induced increase in the TIMP2 expression." (PMID 35414793, 2022). "Mutations in DNMT1 and DNMT3a overexpression are features of both cancer patients and a mouse model of colon tumors; increased DNMT1 and DNMT3a expression contribute to hepatocellular carcinogenesis." (PMID 35054489, 2022). "On the other hand, The expression of DNMT3a is low in normal colonic epithelial cells FHC and primary normal colon epithelial cells 1, 2, and 3, and relatively higher in colon cancer cells (HT-29, HCT 116, HCT-15, SW48, SW480, RKO, and LoVo)." (PMID 34268315, 2021). "We also noticed an inverse relationship between the levels of MTA1 and DNMT3a in NCI-60 Panel cell lines as well as in 59 breast and 61 colon cancer cell lines." (PMID 28393842, 2017). "RRx-001 inhibited the growth of colon cancer cells (HCT 116) and decreased levels of the DNA methyltransferases DNMT1 and DNMT3a in a time and dose-dependent manner." (PMID 28149332, 2017). "Third, the inverse correlation between miR-143 and DNMT3A expression in both colon cancer cell lines and human CRC tissues further consolidates that downregulation of miR-143 resulting in an upregulation of DNMT3A is significant in CRC development." (PMID 19638978, 2009). "These include R-RAS and MASP in GC, MAGE1 in melanoma, S100A4 in colon cancer, PAX2 in endometrial cancer, DNMT3A in testicular germ cell tumours, and various genes in pancreatic cancer." (PMID 19107131, 2009). "We first investigated whether and how DNMT3A regulates hypoxia-induced EMT, using the human colon cancer cell line SW480 as a cellular model." (PMID 40764968, 2025). "Furthermore, the ChIP, MSP, and rescue experiments results confirmed that TDG accelerated the degradation of DNMT3A and significantly regulated the transcription and expression of TIMP2, thereby affecting the migration and invasion of human colon cancer cells." (PMID 35414793, 2022). "In summary, TDG interacts with DNMT3A to promote ubiquitination degradation, induces the hypomethylation of the TIMP2 promoter, increases TIMP2 expression, and significantly inhibits the migration and invasion abilities of human colon cancer cells." (PMID 35414793, 2022). "The fact that DNMT3A and HDAC3 are degraded in methylation-sensitive colon cancer cells in part via blocking their connection with the E3 ubiquitin ligase UHRF1 could explain this decrease in expression." (PMID 35327559, 2022). "Furthermore, in the colon cancer SW480 cells, DNMT3A appears to be recruited by the hypoxia-induced histone mark H3K36me3 to demethylate the HRE in the TWIST1 promoter, thus allowing HIF-1α binding and transcriptional activation of the promoter to initiate the EMT process." (PMID 40764968, 2025). "It should be noted however that PC3 cells contain moderate levels of DNMT1 and DNMT3a which are not affected when DNMT3b is silenced (data not shown); like PC3, colon cancer cells also express DNMT1 and DNMT3a." (PMID 18798999, 2008). "Additionally, the expression of ARID1B was positively correlated with the expression of three methyl transferases (DNMT1, DNMT3A, and DNMT3L) in colon cancer, although the difference was not significant." (PMID 36313455, 2022).
melanoma (32 papers, 2009 to 2025). A malignant, usually aggressive tumor composed of atypical, neoplastic melanocytes. "We present the first known case of a DOS patient who developed early-onset melanoma, associated with a second acquired DNMT3A mutation, suggesting a role for loss-of-function DNMT3A mutations in melanoma initiation." (PMID 37160317, 2023). "We report the case of an adult DOS patient with a germline DNMT3A loss-of-function mutation, who developed an early-onset melanoma with regional lymph node metastatic disease." (PMID 37160317, 2023). "We found that the knockdown of RNA modification regulatory protein encoding genes (METTL4 and DNMT3A) inhibited the ability of melanoma cells to form colonies in soft agar." (PMID 31217906, 2019). "The G protein α-subunit GNAQ is mutated in 46% of uveal melanomas and 84% of blue nevi samples and is less frequently (2.4%) altered in cutaneous melanoma, suggesting that DNMT3A loss of function may be more impactful for melanoma development in certain contexts." (PMID 37160317, 2023). "In seminomas, PRAME expression correlated with TET1, but in melanomas and synovial sarcomas, it correlated with both DNMTs and DNMT3A, respectively." (PMID 38541782, 2024). "In serial sample analysis, we observed that mutations in DNMT3A and TET2 increased in size with longer ICB exposures in the melanoma cohort." (PMID 39456832, 2024). "Conversely, melanomas revealed frequent expression of methyltransferases DNMT3A (49/66, 74%) and DNMT3B (44/66, 67%)." (PMID 38541782, 2024). "Both DNMT3A and DNMT3B manifest oncogenic properties in melanoma and have been linked with unfavorable clinical outcomes." (PMID 38541782, 2024). "Studies in the B16 murine melanoma line, on the other hand, suggested a requirement for functional Dnmt3a in melanoma survival and proliferative capacity." (PMID 37160317, 2023). "Based on this we infer that the upregulated expression of RNA modification regulatory proteins METTL4 and DNMT3A play a key role in melanoma initiation or progression." (PMID 31217906, 2019). "Next, we asked if these RNA-modifying enzyme/proteins (METTL4 and DNMT3A) that are overexpressed in melanoma samples are necessary for its growth." (PMID 31217906, 2019). "Here, our results indicate that TET2 and TET3 are epigenetically silenced by DNMT3A-catalyzed DNA methylation in the TGF-β1-induced EMT-like process in melanoma." (PMID 27852070, 2017). "In summary, our in vitro experiments showed that TET2 and TET3 are suppressors of the EMT-like process in melanoma and DNMT3A-mediated epigenetic silencing is one mechanism by which TGF-β induces an EMT-like process." (PMID 27852070, 2017). "DNMT3a and DNMT3b, the de novo DNA methyltransferases, were shown to have increased expression in metastatic melanomas compared to primary melanomas." (PMID 25885555, 2015). "In the preceding analysis, DNMT3A also exhibited significantly elevated expression levels in the A375 melanoma cells after being induced with the BRAF inhibitor." (PMID 25890285, 2015). "Another group showed that DNMT3a is required for melanoma development and metastasis in a melanoma mouse model." (PMID 25885555, 2015). "Knockdown DNMT3A expression more than doubles the induced 242 genes in melanoma cells and plays an essential role in melanoma tumourigenesis." (PMID 20128888, 2010). "In addition, the depletion of DNMT3A in mouse melanoma cells inhibited tumor growth and metastasis in a xenograft model, while DNMT3B increased proportionally with melanoma progression, leading to the silencing of tumor suppressor gene p16INK4A." (PMID 40136320, 2025). "Also, PRAME IHC positively correlated with both DNMTs and DNMT3A in melanomas and synovial sarcomas, respectively." (PMID 38541782, 2024). "In melanoma, positive associations between expression of PRAME and DNMT3A and DNMT3B were seen." (PMID 38541782, 2024). "This work also shows that DNMT3A is required for melanoma growth in vivo." (PMID 32751889, 2020).